STAT3 (signal transducer and activator of transcription 3)
Diseases named in the same sentence as STAT3 in open-access papers (continued):
Sharing a sentence is not in itself a finding about the gene and the disease.
cancer (continued). "Thus, we concluded that the apoptosis in cancer cells that is modulated by HCCR expression is dependent on STAT3 activity." (PMID 27052330, 2016). "Importantly, the inhibition of JAK/STAT signaling by the STAT3 inhibitor restored GATA6 expression as well as the expression of TFF1/2 in cancer cell lines." (PMID 27598141, 2016). "Altogether, this suggests that inhibiting STAT3 activity may be an effective therapeutic strategy for cancer." (PMID 26683224, 2016). "Interestingly, STAT3 is constitutively phosphorylated in many cancers including canine and human OSA." (PMID 27391430, 2016). "Taken together, these results suggest that GA exerted anti-cancer effect specifically in TKIR cells by inhibiting Src-mediated Stat3 phosphorylation, downregulating Stat3 target genes, especially Bcl2 and cyclin D, hence inducing apoptosis and cell cycle arrest." (PMID 27419630, 2016). "It has been well studied that p- Janus-activated kinase 2 (Jak2) could activate STAT3, and the Jak2/STAT3 signaling pathway is involved in the development of cancers and EMT." (PMID 27121055, 2016). "Despite their potential side effects, inhibition of STAT3 and NF-κB may represent a good approach to combat cancer." (PMID 26474284, 2015). "Therefore, agents that interfere with activated STAT3 are promising for prevention and treatment of cancer." (PMID 25789853, 2015). "Therefore, more STAT3 pathway-specific inhibitors are needed for developing novel anti-cancer drugs." (PMID 26010889, 2015). "Therefore, this novel finding provides a rationale for a combination of MEK inhibitors and STAT3 pathway modulators to afford more effective therapy of K-Ras mutant cancer." (PMID 25961376, 2015). "In addition, another major pathway downstream of Btk that increases cancer progression is mediated by activation of signal transducer and activator of transcription 3 (STAT3)." (PMID 26036311, 2015). "STAT3 has been considered as a promising molecular target for cancer therapy." (PMID 26245871, 2015). "Therefore, in vivo, a dual inhibition of MEK and STAT3 signaling pathways would be much more effective in K-Ras mutant cancer cells." (PMID 25961376, 2015). "Interleukin-6 regulated stem cell-related genes and activated JAK2/STAT3 in cancer cells." (PMID 25797257, 2015). "Moreover, STAT3 knockdown effectively suppressed cancer stem-like properties, synergistically enhanced the chemotherapeutic effect, and significantly improved survival rate in ATRT-CisR-transplanted immunocompromised mice." (PMID 25638155, 2015). "Therefore, further studies should be conducted to address the questions regarding STAT3 in cancer and to find the best efficient strategies that can inhibit the STAT3 activity to gain optimum therapeutic effects." (PMID 26631279, 2015). "STAT3 is constitutively activated at 50–90% frequency in diverse human cancers." (PMID 25671570, 2015). "The STAT3 activation may be important for the MEK inhibitor resistance in these K-Ras mutant cancer cells." (PMID 25961376, 2015). "STAT3 activation alone is sufficient to induce cell transformation, showing a strong oncogenic potential and promotes the maintenance of a procarcinogenic inflammatory microenvironment during cancer initiation and progression." (PMID 28031890, 2015). "Because STAT3 is a critical transcription factor for modulating malignancies among many different cancers, we next aimed to elucidate whether STAT3 enhances Snail expression through transcriptional regulation." (PMID 25638155, 2015). "Targeting the STAT3 pathway directly could be a promising and novel form of treatment for these human cancers." (PMID 26417930, 2015). "Signal transducer and activator of transcription 3 has been shown to be aberrantly activated in a majority of cancers, most commonly secondary to activation of upstream kinases, such as epidermal growth factor receptor and platelet-derived growth factor receptor." (PMID 25914882, 2015).
cancer (continued). "Besides regulating Fascin expression, STAT3 is also involved in the cell proliferation and survival, oncogenesis, and cancer metastasis in GC." (PMID 25992623, 2015). "Interestingly, IL-6, IL-6R and p-STAT3 were expressed in the residual cancer cells of all the patients in the high expression group with poor response to chemoradiotherapy." (PMID 25761055, 2015). "Therefore, we conclude that metformin can block precancerous progression to invasive cancers through inhibiting STAT3-mediated signaling pathways." (PMID 26245871, 2015). "Caspases are cytoplasmic, aspartate-specific cysteine proteases whose activation is required for apoptosis, and increased expression of anti-apoptotic factors by the IL-6/STAT3 signaling pathway may reduce caspase-mediated apoptosis in cancer cells." (PMID 25789077, 2015). "Furthermore, activation of the intracellular Janus kinase (JAK)/STAT3 signaling pathway by IL-6 results in the expression of various genes involved in cancer growth and development." (PMID 25789077, 2015). "Multiple STAT3 activities have been correlated with drug resistance in cancer." (PMID 26106584, 2015). "Stat3 has been shown to promote cell survival and induce drug resistance in cancer cells." (PMID 26625308, 2015). "The mechanism of aberrant STAT3 activation in cancer is not well understood." (PMID 26565811, 2015). "In addition, STAT3 plays a key role in regulating host immune and inflammatory responses and in the pathogenesis of many cancers." (PMID 26199948, 2015). "Moreover, gefitinib improved the cytotoxic activity of natural killer cells against H1975 by modulating the interaction between NK cells and cancer cells, and by inhibiting STAT3 expression." (PMID 25532027, 2015). "As recently suggested, IL-6/STAT3 signaling also promotes stem cell-like phenotype of cancer cells." (PMID 26046794, 2015). "The down-regulation of SIRT-1 expression often observed in cancer may thus contribute to maintain STAT3 activity." (PMID 26106584, 2015). "Interestingly, elevatedlevels of STAT3 have been observed inmany human cancers and cancer cell lines.This review article presents an overview of theJAK/STAT pathway followed by an investigationof the role of STAT3 under normal and malignantconditions." (PMID 26464811, 2015). "Interestingly, earlier studies have shown that PPIs inhibit the expression of proliferation markers in cancer cells through regulation of IL-6/STAT3 pathway." (PMID 26231702, 2015). "Therefore, a comprehensive exploration of the complicated biological behaviors of STAT3 in cancer is direly needed to inhibit the STAT3 signaling pathway." (PMID 26631279, 2015). "Furthermore, the expression of p-STAT3 was investigated in the nucleus of the cancer cells, suggesting that STAT3 signaling is activated through autocrine loop stimulation between IL-6 and IL-6R in OSCC cells." (PMID 25761055, 2015). "EGFR cooperates with STAT3 to induce EMT in cancer cells via increasing Twist gene expression." (PMID 25915156, 2015). "Especially STAT1 and STAT3 display prominent roles in cancer, inflammation and auto-immunity." (PMID 25710482, 2015). "The previous reports show that direct STAT3 suppression induced cancer cell apoptosis." (PMID 26417930, 2015). "Moreover, it is reported that ultraviolet induced cell apoptosis can be repressed by STAT3 activation; whereas STAT3 inhibition induces Caspase dependent apoptosis and inhibits cell migration and angiogenesis in cancer cells." (PMID 25849286, 2015). "To further validate our hypothesis and verify that the effect of resistance to MEK inhibitors is correlated to STAT3 activation, we stably express a known constitutively active STAT3, STAT3-C, in cancer cells." (PMID 25961376, 2015). "However, this is the first study to demonstrate that digoxin can inhibit not only Src but also the phosphorylation and expression of EGFR and STAT3 to further retard cancer cell proliferation, migration and invasion." (PMID 25955608, 2015).
cancer (continued). "STAT proteins (in particular STAT3) are persistently in many cancer-derived cell lines." (PMID 26464811, 2015). "It has been reported that silibinin inhibits STAT3 activation in several preclinical cancer models." (PMID 26510913, 2015). "In summary, this study demonstrates that metformin can block preneoplasm or non-invasive cancer of bladder progressing to invasive cancer through inhibiting STAT3-mediated signaling pathways which can promote viability, proliferation, migration and invasiveness of cancer cells." (PMID 26245871, 2015). "Overall, these data indicate that RXF393-bearing mice offer a unique model to test drugs against cancer cachexia and that sunitinib, as well as sorafenib, can prevent cachexia in vivo by lowering protein catabolism through inhibition of STAT3/MuRF-1 activation at least in muscles." (PMID 25460504, 2015). "Moreover, JAK2-specific inhibition blocks STAT3 phosphorylation and IL-6 production in cancer cells." (PMID 26491227, 2015). "Stat3 and NF-κB signaling pathways play a critical role in cancer cells." (PMID 26169986, 2015). "Also, inhibiting the STAT3 pathway by LY5 enhances the ability of MEK inhibitors to inhibit cancer cell viability." (PMID 25961376, 2015). "These cumulative results suggest that targeting STAT3 may overcome the resistance to EGFR-TKI in cancer cells." (PMID 26542452, 2015). "STAT3 may also participate in gastric carcinogenesis following activation by COX2 in many cancers, such as non-small-cell carcinoma, cholangiocarcinoma, and glioblastoma." (PMID 25331984, 2015). "However, the exact prognostic role of p-STAT3 in cancers with the digestive systems remains to be unsettled." (PMID 26024373, 2015). "The cross talk between miR-155, SOCS1, and STAT3 signaling may provide a new mechanism for inflammation-associated tumorigenesis, which suggests that miR-155 and SOCS1 could potentially be used in cancer therapy." (PMID 26697428, 2015). "An orally bioavailable small-molecule STAT3 inhibitor has been discovered and could be a potential therapeutic agent for human cancer." (PMID 25992623, 2015). "Secretion of IL-11 by TGF-β stimulated CAFs triggers GP-130/STAT-3 signaling in cancer cells." (PMID 25853091, 2015). "We first investigated whether BSN can modulate constitutive STAT3 activation in a variety of human cancer cell lines." (PMID 25788267, 2015). "In addition, MLN8237 down-regulates several oncogenic pathways such as NF-κB, AKT, and STAT3 in cancer cells." (PMID 25987188, 2015). "In bresat cancer, STAT3 activation by EGF treatment induced higher Snail expression and the high expression level of snail was reversed by N-myc downstream-regulated gene 2 (NDRG2) through inhibits STAT3 binding to the Snail promoter and subsequently inhibit the EMT process and cancer progression." (PMID 26631279, 2015). "Transient induction of the Src oncoprotein in a non-transformed breast cell line can initiate an epigenetic switch to a cancer cell via a positive feedback loop that involves activation of the signal transducer and activator of transcription 3 protein (STAT3) and NF-κB transcription factors." (PMID 25784959, 2015). "STAT3 is also involved in regulating the EMT process in several cancer types." (PMID 25638155, 2015). "As such, new directions for cancer therapy by targeting STAT3 should be explored." (PMID 26631279, 2015). "Additionally, constitutive activation of STAT3 in cancer cells led to more malignant cancer phenotypes, including growth, epithelial-mesenchymal transition, migration, invasion, and metastasis." (PMID 26550019, 2015). "Indeed, the levels of transcriptionally active Y-P STAT3 are often elevated in drug-resistant cancer cells." (PMID 26106584, 2015).
cancer (continued). "Moreover, (E)-4-(3-(3,5-dimethoxyphenyl)allyl)-2-methoxyphenol-induced inhibitory effect of cancer cell growth was magnified by knock down of STAT3 with STAT3 siRNA." (PMID 26474284, 2015). "c-Met, a receptor for hepatocyte growth factor (HGF), which is a promoter of cancer progression, has several major alternative downstream pathways in its signaling cascade: Akt 1, 2 and 3 (protein kinase B), signal transducer and activator of transcription 3 (STAT3), and MAPK." (PMID 25633810, 2015). "Important cytokines and mediators involved in the induction and perpetuation of the inflammatory environment in cancer, such as IL-6, IL-1β, macrophage colony-stimulating factor (M-CSF) and cyclooxygenase 2 (Cox2), have the transcription factor STAT3 as a crucial regulator of their expression." (PMID 26501341, 2015). "Therefore, these two proteins, ROCK and STAT-3, are interesting potential therapeutic targets for the treatment of this cancer type." (PMID 26418031, 2015). "However, our data indicated that ERp57 did not translocate from the cytosol to the cell surface in the irradiated cancer cells, and rather, it was observed in the nucleus in a complex with STAT3 in the radioresistant cells." (PMID 25605256, 2015). "However, despite the numerous regulators and pivotal biological functions in cancer, effective therapeutic inventions to inhibit STAT3 and to achieve potent antitumor effects in the clinic have not been identified and still need to be explored further." (PMID 26631279, 2015). "Furthermore, the constitutive activation of STAT3/NF-κB signaling can regulate the Notch pathway, which appears to play a key role in CSCs in a variety of cancers and controls cell fate determination, survival, proliferation, and the maintenance of stem cells." (PMID 26631279, 2015). "Moreover, the activation of epidermal growth factor receptor (EGFR) signaling pathway induces cancer cell EMT via STAT3-mediated Twist gene expression." (PMID 25915156, 2015). "We next determined whether the co-targeting of Src and Stat3 exhibited synergistic activity in RCC cancer cells by treating each of the cell lines with increasing concentrations of dasatinib and CYT387 alone and in combination." (PMID 26625308, 2015). "STAT3, a transcription factor that can promote oncogenesis, is commonly activated in cancer." (PMID 26417930, 2015). "Current anticancer-targeted therapeutics mainly focuses on inhibiting the tyrosine phosphorylation of STAT3, however, epigenetic modification function of STAT3 may present a novel and powerful therapeutic approach for cancer treatment." (PMID 26631279, 2015). "Cixutumumab treatment stimulates STAT3-dependent transcriptional upregulation of IGF-2 in cancer cells and recruitment of macrophages and fibroblasts via paracrine IGF-2/IGF-2R activation, resulting in the stroma-derived CXCL8 production, and thus angiogenic and metastatic environment." (PMID 26465273, 2015). "Interestingly, direct inhibition of STAT3 with Stattic also decreased the fraction of cancer stem cells." (PMID 26287605, 2015). "We hypothesised that therapy-induced stromal IL6 secretion would stimulate STAT3 in neighbouring cancer cells." (PMID 25915429, 2015). "STAT3 decoy ODN provide hope for decoy ODN-based cancer therapy." (PMID 25923701, 2015). "Furthermore, we observed STAT3 blockade delayed the de novo tumorigenesis of mice HNSCC by reducing of stemloid cancer cell." (PMID 26556875, 2015). "STAT3 upregulation in cancers contribute to tumorigenesis and metastatic behavior." (PMID 26389681, 2015). "More and more evidences reveal that blocking STAT3 activation is beneficial for cancer therapy." (PMID 26416445, 2015). "STAT3 constitutes an important therapeutic target because cancer cells depend on the inappropriate activity of this oncogenic transcription factor while normal cells can often tolerate disruption of these proteins with little toxicity due to redundancies in normal signaling pathways." (PMID 26000098, 2015).
cancer (continued). "We further evaluated the effects of STAT3 knockdown on cancer–stroma interaction in vivo." (PMID 26465273, 2015). "As proteins that interact with STAT3 may be key in addressing how STAT3 contributes to cancer pathogenesis, we took a proteomics approach to identify novel STAT3-interacting proteins." (PMID 26000098, 2015). "Blocking constitutive STAT3 signaling in carcinoma cells by STAT3 antisense oligonucleotides, STAT3 small interfering RNAs (siRNAs), or stable transfection of dominant-negative STAT3 can inhibit cancer cell growth, invasion and metastasis, and induce apoptosis." (PMID 26417930, 2015). "STAT3 is critically involved in EGFR-induced cancer cell migration and invasion." (PMID 24662938, 2014). "Thus early research on the role of STAT3 in cancer seemed to clearly indicate that constitutive activation of this protein is a direct driver of cancer pathogenesis." (PMID 24762632, 2014). "In addition, IL-6-induced dimerization of IL-6 receptor activates STAT3, which contributes to cancer progression in cancer inflammatory environment." (PMID 24976685, 2014). "Several genes listed as STAT3 targets exhibit a relevant role in cancer." (PMID 25417721, 2014). "STAT3 promotes cell survival in esophageal, colon, gastric and other types of cancer." (PMID 24743778, 2014). "Nevertheless, independent of whether it is a direct or indirect regulation and how it works precisely, our results demonstrated that negative regulation of STAT3 by STATIP1 appears to be a common issue in distinct cancer cell types." (PMID 25417721, 2014). "Recent evidence suggests a crucial role for STAT family proteins, especially STAT3, in selectively inducing and maintaining a pro-carcinogenic inflammatory microenvironment, both at the initiation of malignant transformation and during cancer progression." (PMID 24675568, 2014). "Blocking of the gp130 signaling pathway, at the JAK level, may be a useful therapeutic approach against cancer owing to the inhibition of STAT3 activity." (PMID 24520293, 2014). "Collectively, these data suggest that TMOC may elicit its anti-cancer activity through inhibition of STAT3 signaling pathway." (PMID 25180593, 2014). "A combined approach of targeting high‐invasive OVCA cells by blockading Gln entry into TCA cycle pathways, along with targeting low‐invasive cancer cells by inhibiting Gln synthesis and STAT3, may provide opportunities for addressing heterogeneity in tumors." (PMID 24799285, 2014). "Importantly, this confirms our premise that Gln exerts oncogenic transformations in high‐invasive cancer cells by differentially activating STAT3 in these cells compared to their low‐invasive counterparts." (PMID 24799285, 2014). "This may not be surprising, given the universe presence of constitutive activation of STAT3 signaling in these cancer cells and their well-characterized prosurvival effect." (PMID 25327561, 2014). "These make STAT3 an excellent molecular candidate for cancer therapy." (PMID 25261365, 2014). "Inhibition of STAT3 promotes the activity of NK and T cells on cancer cells." (PMID 25009822, 2014). "In many types of cancer, by contrast, STAT3 is activated constitutively." (PMID 24762632, 2014). "STAT3 has been shown to induce cancers of the breast, prostate and skin." (PMID 24743777, 2014). "Constitutive STAT3 activation has been reported in 50%–90% of human cancers." (PMID 24518612, 2014). "Thus, inhibiting STAT3 in cancer cells would be a novel approach to reverse immunosuppression and improve results of immunotherapies." (PMID 25333973, 2014).